USP15 (ubiquitin specific peptidase 15)
Diseases named in the same sentence as USP15 in open-access papers (continued):
Sharing a sentence is not in itself a finding about the gene and the disease.
sarcoma (5 papers, 2020 to 2024). A usually aggressive malignant neoplasm of the soft tissue or bone. "In leukemic cells, the USP15 gene interacts with and stabilizes FUS (fused in sarcoma), a DNA repair factor, directly linking USP15 to the DNA damage response, demonstrating the importance of DUBs in preserving normal hematopoiesis." (PMID 37373211, 2023). "Furthermore, in CML cells, USP15 interacts with and increases the stability of FUS (fused in sarcoma), a well-known factor involved in DNA repair." (PMID 39048945, 2024). "USP15 had a positive role in preserving normal stem and leukemic cell genome integrity and mediated the stability of a HSC self-renewal and DNA repair factor, FUS (fused in sarcoma)." (PMID 33378683, 2020).
chronic myelogenous leukemia (4 papers, 2020 to 2022). "USP15 deubiquitinates and stabilizes caspase-6 to increase cell apoptosis in the chronic myeloid leukemia cell K562, and miR-202-5p inhibits the expression of USP15 by directly targeting the 3’ untranslated region (3’UTR) of USP15 to suppress cell apoptosis." (PMID 35203682, 2022).
colorectal cancer (4 papers, 2020 to 2025). A primary or metastatic malignant neoplasm that affects the colon or rectum. "PLOD2 has been reported as an oncogenic gene in colorectal cancer and functions by stabilizing USP15, leading to AKT/mTOR-regulated progrowth signaling." (PMID 40757636, 2025).
epilepsy (4 papers, 2021 to 2024). A brain disorder characterized by episodes of abnormally increased neuronal discharge resulting in transient episodes of sensory or motor neurological dysfunction, or psychic dysfunction. "A series of further experiments is conceivable to advance the understanding of the role of Usp15 in epilepsy to develop approaches for curative therapy." (PMID 37874479, 2024). "It has recently been demonstrated that the expression of ubiquitin-specific peptidase 15 (USP15) was upregulated in a PTZ-kindled (PTZ-K) rat model of epilepsy." (PMID 33643194, 2021). "A recent study revealed the role of USP15 in epilepsy pathogenesis, where USP15 silencing protects against glutamate-mediated neurotoxicity." (PMID 33946990, 2021). "Since these pathways are regulated by ubiquitin-specific proteases (USP), in particular USP15, we hypothesized that USP15 blockade may provide therapeutic relief in treatment-resistant epilepsies." (PMID 37874479, 2024). "Therefore, we next tested how an induced deletion of Usp15 after epilepsy onset would alter spontaneous recurrent epileptic activity, histological hallmarks, and the transcriptome in a long-term experiment." (PMID 37874479, 2024). "Our aim was to determine whether the upstream control of the IFN-α/β, TGF-β, and NRF2 pathways involved in neuroinflammation by blocking USP15 might serve as a treatment for pharmacoresistant epilepsy." (PMID 37874479, 2024). "However, our primary aim was to determine whether targeting USP15 might be a valid strategy for the treatment of chronic epilepsy in patients (i.e., when epilepsy is fully developed where intervention at earlier time points is not possible)." (PMID 37874479, 2024). "Assuming neurons, astrocytes and microglia as the key players of epilepsy, the low effect of Usp15 knockdown in the microglial cell line does not exclude effects in the other cell types." (PMID 37874479, 2024). "As such, it does not invalidate the potential involvement of TGF-β, IFN-α/β and NRF2 pathways, but demonstrates that Usp15 deletion did not impact epilepsy outcomes under the conditions of our experimental setting." (PMID 37874479, 2024). "Our data show that a lack of USP15 is insufficient to modulate the expression of relevant neuroinflammatory pathways in an mTLE mouse model and do not support targeting USP15 as a therapeutic approach for pharmacoresistant epilepsy." (PMID 37874479, 2024). "Likewise, the second experiment series did not provide a hint that deletion of Usp15 following the onset of chronic epilepsy dampens the proinflammatory response and epilepsy-related pathology." (PMID 37874479, 2024). "Interestingly, the knockdown of Usp15, neither in a constitutive fashion, nor conditionally after full development of epilepsy had any major effect on this pattern." (PMID 37874479, 2024).
hepatocellular carcinoma (4 papers, 2022 to 2025). A malignant tumor that arises from hepatocytes. "Second, although USP15 functions as a tumor-inhibiting factor, its knockout in lung and hepatocellular cancer cells promotes malignant phenotype transformation, including increased proliferation and metastasis." (PMID 39522000, 2024). "Recent reports indicate that USP15 is highly expressed in liver cancer tissues compared with normal tissues, and the knockdown of USP15 inhibits cell proliferation and enhances cell apoptosis in the hepatocellular carcinoma cell lines SNU449 and Hep3B." (PMID 35203682, 2022).
liver cancer (4 papers, 2022 to 2023). An epithelial or non-epithelial malignant neoplasm that arises from the liver. "In our PPI network of USP15, we identified nHCC = 143 known liver cancer genes (mutation rate > 1%)." (PMID 36900163, 2023). "The USP15 expression levels in tissue samples of liver cancer were significantly lower than those in normal tissue (p < 0.0001, Mann–Whitney U test)." (PMID 36900163, 2023). "The results motivated a more detailed investigation of the function of USP15 and its potential role as a tumor-suppressing gene in liver cancer." (PMID 36900163, 2023). "USP15 is highly expressed in liver cancer tissues and cell lines, and high expression is significantly positively correlated with HCC recurrence." (PMID 35875077, 2022). "Studies have shown that downregulation of USP15 expression can inhibit the proliferation and apoptosis of liver cancer cells." (PMID 35875077, 2022). "USP15 deubiquitinates and stabilizes the hepatitis B virus X (HBx) protein in the human liver cancer cells Huh7, HepG2, and Hep3B." (PMID 35203682, 2022). "A set 105 interaction partners of USP15 contained two liver cancer genes, LRRK and NOTCH1." (PMID 36900163, 2023). "Motivated by the experimental evidence of a regulation by USP15 for eight exemplary members of the human USP15 PPI network, we chose all liver cancer genes with a mutation rate of over 1% (295 genes) in the database cBioPortal for Cancer Genomics (dataset: HCC, TCGA, PanCancer Atlas)." (PMID 36900163, 2023). "In addition, xanthine oxidoreductase (XOR) can interact with USP15 to enhance the stability of Kelch-like ECH-associated protein 1 (KEAP1), which ultimately promotes the accumulation of reactive oxygen species (ROS) and liver cancer stem cells (CSCs)." (PMID 35875077, 2022).
multiple myeloma (4 papers, 2018 to 2022). "One study in multiple myeloma models revealed that USP15 transcripts increase in response to LPS stimulation and NF-κB activation." (PMID 34465865, 2022). "However, the underlying mechanism by which USP15 regulates multiple myeloma (MM) cell proliferation and apoptosis has not been established." (PMID 30459344, 2018).
prostate carcinoma (4 papers, 2018 to 2022). A carcinoma that arises from epithelial cells of the prostate gland. "Nedd4-mediated IRS-2 ubiquitination is inhibited by USP15 to attenuate downstream IGF-I signaling in prostate cancer PC-3 cells." (PMID 33946990, 2021). "However, IRS2 only binds to USP15 after it is connected to the ubiquitin molecule, thereby blocking IGF1-dependent IRS2 phosphorylation to weaken IGF-I signaling in prostate cancer PC-3 cells." (PMID 35203682, 2022).
colon cancer (3 papers, 2022 to 2025). "Moreover, previous studies have shown that USP15 promotes colon cancer proliferation and invasion via the AKT/mTOR pathway." (PMID 39794359, 2025).
glioma (3 papers, 2018 to 2025). A benign or malignant brain and spinal cord tumor that arises from glial cells (astrocytes, oligodendrocytes, ependymal cells). "Inhibition of USP15 expression reduces the oncogenic capacity of patient-derived glioma-initiating cells." (PMID 40034124, 2025). "Reducing TGF-β signaling by depleting USP15 reduces the oncogenicity of patient-derived glioma-initiating cells, indicating the therapeutic capabilities of USP15 inhibition." (PMID 32549302, 2020). "Depletion of USP15 represses the oncogenic ability of patient-derived glioma-initiating cells." (PMID 29593334, 2018).
lung adenocarcinoma (3 papers, 2018 to 2022). A carcinoma that arises from the lung and is characterized by the presence of malignant glandular epithelial cells. "Of note, alterations in USP15 are associated with worse prognosis within this cohort of lung adenocarcinoma patients." (PMID 29429988, 2018). "Therefore, we explored whether the expression of USP15 was implicated in the progression of human lung adenocarcinoma." (PMID 35422093, 2022). "We are further investigating the relationship between cellular location of USP15 and tumor malignancy during lung adenocarcinoma progression." (PMID 35027535, 2022). "Consistently, the expression of USP15 was significantly downregulated in patients with primary lung adenocarcinoma." (PMID 35422093, 2022). "In relation to our data for A549 cells, we examined the provisional TCGA data set for lung adenocarcinoma and found that USP15 is altered in 30 of 230 cases (13%), most commonly being amplified and/or overexpressed." (PMID 29429988, 2018). "We found that A549 lung adenocarcinoma cells express both USP15 isoforms, with higher levels of isoform-1, which can be distinguished by isoform-specific small interfering RNAs (siRNAs) and reverse transcription-PCR (RT-PCR) primers." (PMID 29429988, 2018). "Together these data suggest that increased expression of USP15 in lung adenocarcinoma is biased towards higher expression of isoform-1, which once S229-phosphorylated is less able to protect against micronuclei formation through mitotic mis-segregation." (PMID 29429988, 2018). "Importantly, TCGA data analysis revealed that USP15 was significantly downregulated in lung adenocarcinoma (LUAD) and lung squamous cell carcinoma (LUSC)." (PMID 35422093, 2022). "Similarly, our current study found an altered USP15 expression in lung adenocarcinoma, which is correlated to LUAD development and contributes to poorer disease-specific survival." (PMID 35027535, 2022). "Additionally, the alteration frequency of USP15 in TCGA-LUAD data showed an increased USP15 expression that contributes to lung adenocarcinoma (LUAD) development." (PMID 35027535, 2022). "Next, we further investigated if USP15 might be expressed in normal and tumor tissues and if USP15 might be increased in tumor tissues of lung adenocarcinoma." (PMID 35027535, 2022). "From tissue arrays, we observed the expression of USP15 in lung adenocarcinomas." (PMID 35027535, 2022). "The increased USP15 expression contributes to the lung adenocarcinoma (LUAD) development and shows significantly lower disease-specific survival of patients with USP15 alteration." (PMID 35027535, 2022). "Notably, the downregulation of USP15 was significant in primary non-small cell lung cancer (NSCLC) patients, especially in patients with lung adenocarcinoma." (PMID 35422093, 2022).
non-small cell lung carcinoma (3 papers, 2022 to 2023). A group of at least three distinct histological types of lung cancer, including non-small cell squamous cell carcinoma, adenocarcinoma, and large cell carcinoma. "Fang and colleagues have reported that miR-30c-2-3p targeted TGFBR2 and USP15 in non-small cell lung cancer (NSCLC) cells, leading to the inactivation of TGF-β signaling." (PMID 36606578, 2023). "It has been reported that the knockdown of USP15 results in the expression decrease in the topoisomerase II α (TOP2A) protein, instead of mRNA, in the human non-small cell lung cancer cell line A549, indicating that USP15 regulates TOP2A to maintain genome integrity." (PMID 35203682, 2022).
osteoarthritis (3 papers, 2021 to 2025). A noninflammatory degenerative joint disease occurring chiefly in older persons, characterized by degeneration of the articular cartilage, hypertrophy of bone at the margins and changes in the synovial membrane. "Moreover, overexpression of USP15 can repair the joint plane in the rat osteoarthritis model, showing that USP15 plays an important role in preventing cartilage damage in vivo and in vitro." (PMID 35203682, 2022). "USP15 deubiquitinates and interacts with the extracellular-signal-regulated kinase 2 (ERK2), but it does not regulate the stability of ERK2, resulting in an increase in the pERK1/2 levels to further enhance the TGFβ/SMAD2 signaling pathway and suppress osteoarthritis progression." (PMID 35203682, 2022).
osteosarcoma (3 papers, 2014 to 2024). A usually aggressive malignant bone-forming mesenchymal neoplasm, predominantly affecting adolescents and young adults. "Spontaneous genotoxic stress was also observed in USP15 depleted osteosarcoma cells, thereby extending the validity of USP15 expression as genome integrity safeguard mechanism to multiple tissue neoplasia." (PMID 33378683, 2020). "USP15 is mutated or inactivated in several cancers, but data about its role in osteosarcoma are lacking, thus further research on USP15’s role in osteosarcoma is required to evaluate its possible targeting for therapy." (PMID 38534381, 2024).
bladder cancer (2 papers, 2024 to 2025). "The results revealed that excessive expression of BRCC3 promoted the growth, invasion, and migration of bladder cancer cells and also counteracted the reduced proliferation and invasion caused by the inhibition of USP15 expression." (PMID 38656882, 2024). "Collectively, these findings provide compelling evidence that USP15 is significantly dysregulated in bladder cancer and is associated with an unfavorable prognosis." (PMID 38656882, 2024). "The expression of USP15 was associated with the proliferation, migration and invasiveness of bladder cancer." (PMID 38656882, 2024). "Overall, our experimental results provide compelling evidence supporting the notion that curtailing USP15 expression holds the potential to impede the progression of bladder cancer." (PMID 38656882, 2024). "The findings revealed a positive correlation between USP15 expression and the NF-κB pathway, which is known to play a crucial role in driving bladder cancer development." (PMID 38656882, 2024). "Our experimental findings suggest that USP15 effectively modulates the NF-κB pathway, thereby amplifying bladder cancer cell proliferation through its influence on p-P65 protein expression." (PMID 38656882, 2024). "USP15 induced bladder cancer progression through reducing the degradation of BRCC3, thereby regulating the classical NF-κB signaling pathway." (PMID 38656882, 2024). "Despite a wealth of research on the oncogenic functions of USP15 in various malignancies, scant attention has been given to understanding its precise role in bladder cancer." (PMID 38656882, 2024). "Strikingly, attenuation of USP15 expression greatly attenuated the proliferation, migration, and invasion of bladder cancer cells." (PMID 38656882, 2024). "In summary, our research underscores the influential role of USP15 in shaping the progression and prognosis of bladder cancer." (PMID 38656882, 2024). "Evidently, USP15 promotes the development of bladder cancer by stabilizing BRCC3, thereby activating the NF-κB signaling pathway." (PMID 38656882, 2024). "As anticipated, the results demonstrated noticeably higher levels of USP15 protein expression in bladder cancer cells (T24, J82, and UM-UC-3) compared to normal bladder cells." (PMID 38656882, 2024). "Collectively, these results strongly suggest that USP15 promotes the proliferation, invasion, and migration of bladder cancer cells through the NF-κB pathway." (PMID 38656882, 2024). "Overall, our findings elucidated the carcinogenic effects of USP15 in bladder cancer, primarily mediated by the excessive activation of the NF-κB signaling pathway, thereby promoting tumor development." (PMID 38656882, 2024). "To further delve into the functional enrichment of USP15 in bladder cancer, we utilized LinkedOmics for GSEA analysis." (PMID 38656882, 2024). "Through its regulation of BRCC3 expression, USP15 exerts control over the multiplication, invasiveness, and migration of bladder cancer cells." (PMID 38656882, 2024). "Our study shed light on the significant overexpression of USP15 in bladder cancer cells compared to normal bladder cells, correlating with a poorer prognosis for bladder cancer patients." (PMID 38656882, 2024). "Taken together, our comprehensive analysis establishes USP15 as a promoter of bladder cancer cell multiplication and invasion, primarily achieved through its activation of the NF-κB pathway." (PMID 38656882, 2024). "In summary, we have uncovered the hitherto unexplored role of USP15 in bladder cancer, documenting its overexpression in bladder cancer tissues." (PMID 38656882, 2024). "Moreover, of utmost significance, our research has uncovered the regulatory mechanism by which USP15 influences the NF-κB pathway in bladder cancer—a breakthrough in our understanding of this complex interplay." (PMID 38656882, 2024).